EGFR (epidermal growth factor receptor)
Diseases named in the same sentence as EGFR in open-access papers (continued):
Sharing a sentence is not in itself a finding about the gene and the disease.
pancreatic cancer (continued). "Furthermore, they found that NRF2 deficiency resulted in defective autocrine epidermal growth factor receptor (EGFR) signaling and oxidation of specific translational regulatory proteins, thereby leading to impaired cap-dependent and cap-independent mRNA translation in pancreatic cancer cells." (PMID 34502181, 2021). "Pancreatic cancer treated with CT, a selective STAT3 inhibitor, and Gefitinib (EGFR inhibitor) also showed encouraging results with the lowest time capable of inducing cell death in all eight pancreatic cancer cells examined." (PMID 33544704, 2021). "Epidermal growth factor receptor (EGFR) blockage in PDAC previously reported with disappointing outcomes and dampened the enthusiasm in the examination of RTKs for pancreatic cancer therapy." (PMID 34479614, 2021). "The PDACEV signature calculated as the unweighted sum of EGFR, EPCAM, MUC1, GPC1, and WNT2 signals showed an 86% sensitivity and 81% specificity in distinguishing pancreatic cancer patients from healthy controls." (PMID 33803470, 2021). "In pancreatic cancer (PC) cell lines, FEZF1-AS1 served as an oncogene to induce cell proliferation and invasion through miR-133a/EGFR axis under normoxic condition." (PMID 33391416, 2021). "Erlotinib is an epidermal growth factor receptor (EGFR) inhibitor in use for the treatment of non-small cell lung cancer (NSCLC) and pancreatic cancer." (PMID 34615934, 2021). "A previous study has been shown that PRMT5 regulates the autophosphorylation of EGFR at Tyr1068 and Tyr1172 to promotes EMT in pancreatic cancer cells." (PMID 33495409, 2021). "Alternatively, pancreatic cancer cells, through the KDM3A-mediated overexpression of EGFR decrease T-cell infiltration." (PMID 33671588, 2021). "A previous study revealed that EFEMP1 bound EGFR, activating the MAPK and Akt pathways to promote tumour growth in pancreatic carcinoma cells." (PMID 34936728, 2021). "Regulation of EGFR is at least partially mediated by NDRG1, which is in accordance with the results observed in pancreatic carcinoma." (PMID 35008802, 2021). "Erlotinib is an epidermal growth factor receptor (EGFR) tyrosine kinase inhibitor (TKI) and has been widely used in EGFR mutant advanced NSCLC patients 36 and advanced pancreatic cancer patients." (PMID 31942177, 2020). "KPT-185 significantly inhibits cancer cell proliferation and induces cell-cycle arrest and apoptosis, such as cancer cells from acute myeloid leukemia, pancreatic cancer and NSCLC, including EGFR-TKI-resistant cell lines." (PMID 32923394, 2020). "Specifically, studies have reported the over-expression of EGFR and HER-2 in patient pancreatic cancer tissue (45–95% and 43–69%, respectively) and patient head and neck squamous cell carcinoma tissue (up to 90% and 68%, respectively)." (PMID 32726945, 2020). "Our study revealed that pancreatic cancer cells also expressed a functional P2Y12, which is required for cell proliferation by promoting EGFR-dependent and independent AKT-mediated survival signalling." (PMID 31968611, 2020). "RAF1 fusion was detected in 4 cases (GC, melanoma, STS, and pancreatic cancer), BRAF fusion in 2 cases (BTC and STS), ALK fusion in 2 cases (CRC and BTC), ROS1 fusion in 1 case (CRC), and EGFR fusion in 1 case (CRC) with diverse counterparts." (PMID 32411236, 2020). "Another study has indicated that the use of galectin-3 inhibitors can block the binding of galectin-3 to EGFR, thus inhibit the galectin-3/EGFR/Akt/FOXO3 axis and inhibit the occurrence and development of pancreatic cancer in vivo and in vitro." (PMID 30996686, 2019). "Kaempferol dose-dependently inhibits the growth of pancreatic cancer cells, SNU-213, Panic-1, and Miapaca-2, through inducing apoptosis and effectively inhibiting cell migration, ERK1/2, epidermal growth factor receptor (EGFR)-related Src, and AKT pathways." (PMID 31248102, 2019).
pancreatic cancer (continued). "It has been reported that EGFR is required for KRAS-induced pancreatic tumorigenesis and therefore served as a therapeutic target for pancreatic cancer." (PMID 31514441, 2019). "To further confirm that MYST1 promoted cell proliferation through EGFR activation, we used an EGFR inhibitor, erlotinib, which was used to treat NSCLC, pancreatic cancer and several other types of cancer." (PMID 31691527, 2019). "In our attempt to seek novel strategy to treat pancreatic cancer, we found that VPA exhibits a promising anti-tumor activity selectively against EGFR/ErbB2/ErbB3-coexpressing pancreatic cancer." (PMID 30961642, 2019). "Previously, we found that SM is unambiguously docked to EGFR and probably inhibits its activity; Liby and colleagues showed that CDDO-Im can directly bind to the receptor (3 μM; PDA 4964 pancreatic cancer cells (1 h))." (PMID 31523389, 2019). "To determine the role of Ajuba in SP1-mediated transcriptional regulation, we examined the mRNA level of the best known SP1target genes EGFR and IGF1R in pancreatic cancer Patu8988 cells used for cell growth assays by using qRT-PCR approach." (PMID 31101117, 2019). "Phosphorylation of EGFR and AKT were significantly reduced in primary pancreatic tumors, spleen and liver tissues where metastasis was observed." (PMID 30899425, 2019). "Consistently, direct activation of either ErbB3 or EGFR signaling with specific ligands (NRG-1 and EGF, respectively) also resulted in significant abrogation of anti-pancreatic cancer activity of VPA." (PMID 30961642, 2019). "DTLP was shown specifically binding to EGFR and HER2 on cell surface, followed by endocytosis into cytoplasm of pancreatic cancer cells." (PMID 30681288, 2019). "For example, as in many other cancers, amplification and overexpression of EGFR activates oncogenic MEK and PI3K signalling in pancreatic cancers, even those harbouring mutant RAS42." (PMID 31527715, 2019). "To target NPs to pancreatic cancer cells, we used EGFR inhibitors, ERL and CET, since EGFR overexpression has been found in 90% of pancreatic cancers." (PMID 31694306, 2019). "For example, a phase III trial demonstrated that the combination of erlotinib, a first-generation EGFR-TKI, and gemcitabine improved the survival of patients with advanced pancreatic cancer; however, this improvement was limited." (PMID 31614999, 2019). "A very recent study showed that RNase A and angiogenin activate the EGFR-ERK pathway and AKT to promote proliferation of pancreatic cancer cells." (PMID 30534052, 2018). "It has also been shown that EGFR and MUC1 will accumulate in the perinuclear space in pancreatic cancer cells after exposure to EGF stimuli, similar to our current findings." (PMID 29464085, 2018). "Receptor tyrosine kinases including EGFR, PDGFRα (platelet-derived growth factor receptor-α), and VEGFR (vascular endothelial growth factor receptor) have been detected to be activated in pancreatic cancer." (PMID 30643798, 2018). "The epidermal growth factor receptor (EGFR) pathway substrate 8 (Eps8) is a TAA that is frequently overexpressed in breast, colon, and pancreatic cancers and other malignancies but rarely in normal tissues." (PMID 29515106, 2018). "The epidermal growth factor receptor (EGFR), which activates STAT3, is reportedly overexpressed in human pancreatic cancer cells." (PMID 30400136, 2018). "Erlotinib, an EGFR tyrosine kinase inhibitor (TKI), is used for the treatment of non-small cell lung cancer (NSCLC) and pancreatic cancer." (PMID 30326853, 2018). "Erlotinib, a tyrosine kinase inhibitor (TKI) of the epidermal growth factor receptor (EGFR), is the only RTK targeting agent, which has been approved for treatment of advanced pancreatic cancer but with minor clinical effect." (PMID 29856777, 2018). "Here, the antitumor activity of KAN0439834 was explored in vitro using a panel of eight human pancreatic carcinoma cell lines expressing the phosphorylated full-length ROR1 and EGFR." (PMID 29856777, 2018).
pancreatic cancer (continued). "Preclinical studies evaluating combination therapy with EGFR and RAS pathway inhibitors in pancreatic cancer have shown promising results." (PMID 29262554, 2017). "This activity results in inhibition of pancreatic cancer cell growth and migration, decreased colony formation, as well as downregulation of a plethora of pathways pivotal for PDAC progression, including EGFR, ERK or KRAS expression." (PMID 28640192, 2017). "Ligands of EGFR, including EGF and TGF-alpha, have been observed to be overexpressed in the majority of pancreatic cancer types." (PMID 27999198, 2017). "According to our previous study, EGFR, functioning as a REG3A receptor, mediated the REG3A signal-promoting human pancreatic cancer cell growth and JAK2/STAT3 activation." (PMID 28880262, 2017). "Overexpression of miR-146a inhibits the proliferation and survival of breast, prostate, and pancreatic cancer cells through the downregulation of its targets including ROCK1, EGFR, and MTA-2." (PMID 28435518, 2017). "A significantly higher incidence of high expression of both EGFR and HAb18G/CD147 was found in pancreatic cancer tissues compared with normal tissues (71.57% [73/102] vs. 17.02% [8/47], P < 0.001)." (PMID 27556697, 2016). "Previous studies have demonstrated higher EGFR and EGF expression in pancreatic cancer tissue compared to normal pancreatic tissue." (PMID 27788491, 2016). "In particular, the fact that EGFR and hepatocyte growth factor receptor (HGFR) were targets in pancreatic cancers to kaempferol was most inspiring." (PMID 27175782, 2016). "In conclusion, our study suggests that pancreatic cancer cells actively respond to short-term gemcitabine stress by inducing invasion via up-regulating HAb18G/CD147 and activating downstream EGFR-pSTAT3 signaling." (PMID 27556697, 2016). "Next, we analyzed the co-expression of EGFR and HAb18G/CD147 in 47 normal pancreas and 102 pancreatic cancer tissues with positive staining for both antigens." (PMID 27556697, 2016). "To investigate whether the expression levels of HAb18G/CD147 and EGFR are associated in human pancreatic cancer, we firstly analyzed EGFR mRNA expression levels in 7 pairs of pancreatic cancer and adjacent non-tumor tissues from patients with pancreatic cancer." (PMID 27556697, 2016). "Collectively, these results clearly indicate that kaempferol efficiently inhibits the migratory activity by blocking the EGFR related Src, AKT, and ERK1/2 signaling pathway in human pancreatic cancer cells." (PMID 27175782, 2016). "Gefinitib also inhibited the phosphoylation of EGFR, Src, AKT, and ERK1/2 pathway, and furthermore pretreatment of gefinitib diminished the effect of kaempferol on migration of pancreatic cancer cells." (PMID 27175782, 2016). "In response to short-term gemcitabine stress, pancreatic cancer cells accelerate invasion by up-regulating HAb18G/CD147 expression and activating HAb18G/CD147 downstream of EGFR-pSTAT3 signaling." (PMID 27556697, 2016). "We selected 24 pancreatic cancer cell targets of kaempferol using the TCMSP database; they included six receptors including epidermal growth factor receptor (EGFR), 16 kinases, and two unclassified-proteins." (PMID 27175782, 2016). "SB.06 cells showed increased resistance to both anti-EGFR and anti-PI3K inhibition compared to SB.07 and other tested pancreas cancer lines as measured by ≥3 to 10-fold higher IC50 values in treated SB.06 cells compared to other lines." (PMID 26962861, 2016). "Epidermal growth factor receptor (EGFR) is overexpressed in a variety of malignancies, including cancers of pancreas, breast, head and neck, lung and ovary." (PMID 27129169, 2016). "Erlotinib inhibits ATP-binding of the EGFR tyrosine kinase and is approved for treatment of metastatic NSCLC and advanced pancreatic cancer." (PMID 27150056, 2016).
pancreatic cancer (continued). "Compounds active against at least one of the main target kinases (EGFR and/or class III RTKs) were screened for their cytotoxic potential against lung and pancreatic cancer cell lines." (PMID 26568452, 2015). "We found that combined treatment with the IGF-IR and EGFR/Her-2 inhibitors NVP-AEW541 and lapatinib, respectively, synergistically inhibited pancreatic cancer cell growth." (PMID 25886138, 2015). "Most pancreatic carcinomas (95%) aberrantly express EGFR, HER2 and HER3 receptors and their cognate ligands, promoting constitutive activation of EGFR family members that result in pancreatic cancer cell proliferation." (PMID 25686822, 2015). "ErbB-1 (EGFR) and ErbB-2 (HER2/neu) expression is found in 90% and 21% of pancreatic cancers, respectively." (PMID 25935754, 2015). "Transmembrane proteins MUC4, EGFR and HER2 are shown to be critical in invasion and metastasis of pancreatic cancer." (PMID 25686822, 2015). "Erlotinib, an epidermal growth factor receptor (EGFR) tyrosine kinase inhibitor (TKI), is the only biologic agent that has been approved for the treatment of advanced pancreatic cancer (APC)." (PMID 25935754, 2015). "In summary, our study discloses a novel mechanism of AZD8055 induction of pancreatic cancer cell resistance, which is dependent on AKT inhibition-induced EGFR upregulation." (PMID 25654224, 2015). "Erlotinib, a selective epidermal growth factor receptor (EGFR) tyrosine kinase inhibitor (TKI), is an orally active agent for advanced NSCLC and pancreatic cancer." (PMID 26046796, 2015). "In recent years preclinical data suggest that addition of Epidermal Growth Factor Receptor (EGFR) inhibitors can increase the activity of the use of gemcitabine and radiation in pancreatic cancer cell lines and tumors." (PMID 26670587, 2015). "Clinical trials evaluating newer EGFR TKIs such as afatinib (NCT01728818) and dacomitinib (NCT02039336) in pancreatic cancer are currently underway." (PMID 25935754, 2015). "Based on these findings, we conclude that pan-EGFR inhibitor (canertinib or afatinib) will specifically down regulate EGFR and HER2 and result in an anti-proliferative effect in pancreatic cancer cells." (PMID 25686822, 2015). "The expression and role of epidermal growth factor receptors (EGFR/HER1 and HER2) have been widely studied, including in pancreatic cancer." (PMID 25918250, 2015). "Many studies have indicated that the EGFR/AKT/p21 and EGFR/SRC/E-cadherin pathways play key roles in the proliferation, cell cycle control, migration and invasion of pancreatic cancer cells." (PMID 25635996, 2015). "However, the importance of EGFR mutations in pancreatic cancer has not been investigated until now." (PMID 26046796, 2015). "A recent study showed that single nucleotide polymorphisms of the β2-AR gene were associated with LNM, poor prognosis, and high expression levels of β2-AR, EGFR, VEGF, and MMP-2 in pancreatic carcinoma." (PMID 26526356, 2015). "MUC4 stabilizes HER2 on the plasma membrane by inhibiting its internalization in pancreatic cancer, whereas MUC1 induces the internalization of EGFR and directs it to the nucleus for transcriptional upregulation of oncogenic factors." (PMID 25261375, 2014). "SMAD4 has been shown to influence EGFR and VEGF expression in human normal pancreatic ductal cells (HPDEC) and Hs766T human pancreatic cancer cells." (PMID 24625091, 2014). "In the present study, we identified that EGFR, a Hsp90 client, is regulated by CHIP through ubiquitination in pancreatic cancer cells." (PMID 24722501, 2014). "Using immunohistochemistry analysis, we also found that expression of HER-2 and EGFR was increased in the HPNE/K-ras/p16sh tumors compared with human normal pancreatic duct, similar to human pancreatic cancers." (PMID 25029561, 2014). "We thus decided to additionally analyze downstream targets of the EGFR pathway, namely phospho-ERK (pERK) and phospho-AKT (pAKT) as potential biomarkers in advanced pancreatic cancer." (PMID 25164437, 2014).
pancreatic cancer (continued). "As compared to other pancreatic carcinoma cell lines, HPDE cells express relatively lower levels of EGFR, erbB2, TGF-α, HGFR, VEGF and KGF." (PMID 25373319, 2014). "A prognostic study in Chinese patients with pancreatic cancer indicated that the median survival rates were 17.2 months and 9.7 months for the EGF (-) EGFR (-) group and EGF (+) EGFR (+) group, respectively." (PMID 24130758, 2013). "The aim of this study was to investigate the sensitivity of the same panel of pancreatic cancer cell lines to treatment with an IGF-IR TKI, NVP-AEW541, when used alone or in combination with afatinib, anti-EGFR mAb ICR62 or gemcitabine." (PMID 23367880, 2013). "The sensitivity of a panel of human pancreatic cancer cell lines to treatment with NVP-AEW541 used alone or in combination with afatinib, anti-EGFR antibody ICR62, and cytotoxic agents was determined using the Sulforhodamine B colorimetric assay." (PMID 23367880, 2013). "We have reported recently the superiority of afatinib compared to our anti-EGFR mAb ICR62 and erlotinib in inhibiting the growth of a panel of human pancreatic cancer cell lines." (PMID 23367880, 2013). "The EGFR/MAPK and PI3K/Akt/mTOR pathways are often dysregulated and considerable evidence supports the important role of these pathways in the biology of pancreatic cancer." (PMID 22367239, 2013). "Epidermal growth factor receptor (EGFR) family is the plasma membrane glycoprotein and was shown to play a crucial role in pancreatic cancer initiation and development." (PMID 22848379, 2012). "In pancreatic cancer, HER3 is a preferred dimerization partner for EGFR and through the PI3 K/Akt pathway plays a role in modulating response to erlotinib." (PMID 23198146, 2012). "There is a sound rationale for combining a human epidermal growth factor receptor type 1 (HER1/EGFR) inhibitor and gemcitabine in pancreatic cancer." (PMID 21922022, 2011). "While EGF first stimulates the activation of EGFR, and subsequently induces pancreatic cancer cell proliferation, concurrent EGF-induced the activation of ROCK then turns off the activated EGFR pathway." (PMID 21722395, 2011). "The ubiquitous EGFR exhibited significantly decreased cell surface expression at cell densities near confluence in BxPC-3 and MIA PaCa-2 pancreatic cancer as well as HT-29 colon cancer cells, in contrast to NTR1." (PMID 24212612, 2011). "The CAF–AsPC-1 pancreatic cancer xenografts reached significantly greater tumour volume than those xenografts lacking CAF and were resistant to the anti-tumour effects of EGFR inhibition with erlotinib." (PMID 21792199, 2011). "By analogy, and given the presence of EGFR-ErbB3 heterodimers in pancreatic cancer cells, we postulated that NRG-1, a specific ErbB3 ligand, is secreted by the stroma, forms an active paracrine loop and influences response to EGFR inhibition by erlotinib." (PMID 21792199, 2011). "A monoclonal antibody against HER1/EGFR, cetuximab, has been demonstrated to be effective in pancreatic cancer when combined with gemcitabine." (PMID 24212633, 2011). "Using NanoDLSayTM, we have further discovered a new heteromeric protein complex that is formed between epidermal growth factor receptor (EGFR), Src and Stat3 in pancreatic cancer cells." (PMID 21605409, 2011). "A recent phase III trial combining erlotinib, an oral HER1/EGFR tyrosine kinase inhibitor, with gemcitabine is the first to demonstrate statistically significant improved survival in advanced pancreatic cancer." (PMID 21044336, 2010). "EGFR pathway genes, including, EGFR, KRAS, BRAF, and PIK3CA genes, are well-investigated oncogenes in many tumors including lung, colorectal (CRC), and pancreatic cancers (PAC)." (PMID 19826477, 2009). "The tyrosine kinase epidermal growth factor receptor (EGF-R) and its ligands are expressed in pancreatic cancer tissues, and this coexpression seems to be correlated with tumour progression." (PMID 27994708, 2008).